BRINP1 (BMP/retinoic acid inducible neural specific 1)
Description:
Plays a role in neurogenesis and brain development (By similarity). May suppress cell cycle progression in postmitotic neurons by inhibiting G1/S transition.
Synonyms: DBC1; DBCCR1; FAM5A
Tractability: Antibody: UniProt predicts a signal peptide or a membrane-spanning region. PROTAC: its protein half-life has been measured.
Gene: Protein-coding gene on chromosome 9 (119,153,458 to 119,369,515, reverse strand). Ensembl gene ENSG00000078725.
Subcellular location: Cytoplasm
Subcellular location (Human Protein Atlas): Microtubules
Gene Ontology:
Molecular function: protein binding
Biological process: cellular response to retinoic acid; central nervous system neuron differentiation; negative regulation of mitotic cell cycle; brain development; central nervous system neuron development; positive regulation of neuron differentiation
Cellular component: cytoplasm; dendrite; neuronal cell body; glutamatergic synapse; synapse
Genetic constraint (gnomAD): Loss-of-function variants: 14 observed, 70.07 expected, observed/expected ratio (o/e) 0.2, 90% interval 0.13 to 0.31. The upper end of that interval is the gene's LOEUF score, 0.31, which puts it in group 1 of 6, group 1 being the genes least tolerant of losing a copy. Missense variants: 831 observed, 1,005.1 expected, observed/expected ratio (o/e) 0.83, 90% interval 0.78 to 0.88. Synonymous variants: 402 observed, 382.8 expected, observed/expected ratio (o/e) 1.05, 90% interval 0.97 to 1.14.
Homologues: Orthologues: chimpanzee BRINP1 (100% identical), macaque BRINP1 (100% identical), pig BRINP1 (99% identical), rabbit BRINP1 (99% identical), guinea pig BRINP1 (99% identical), rat Brinp1 (99% identical), mouse Brinp1 (99% identical), dog BRINP1 (93% identical), tropical clawed frog brinp1 (84% identical), zebrafish brinp1 (84% identical). Paralogues in human: BRINP3 (53% identical), BRINP2 (52% identical).
Diseases named in the same sentence as BRINP1 in open-access papers:
BRINP1 is named in the same sentence as 40 diseases in open-access papers, as found by Europe PMC text mining. Sharing a sentence is not in itself a finding about the gene and the disease. The quoted sentences say what the papers report.
bladder cancer (13 papers, 2004 to 2022). "Subsequently, it was observed that ectopically expressing BRINP1 caused cell cycle arrest in cultured cell lines such as bladder cancer cells and the NIH 3T3 cell line, or even mouse embryonic stem cell-derived neural stem cells." (PMID 28630152, 2017). "Other candidates include BRINP1 (silenced in some bladder cancers), CD7 (associated with leukaemia), CSTA (encodes a stefin that functions as a cysteine protease inhibitor, suggested as a prognostic tool for cancer), and SUPT20H (a known tumour rejection antigen)." (PMID 32872585, 2020). "BRINP1 was initially identified as a tumour suppressor protein in human bladder cancer, as part of an effort to locate tumour suppressor genes in bladder cancer cells, and was given the name DBCCR1 (deleted in bladder cancer chromosome region 1)." (PMID 28630152, 2017).
Anxiety (4 papers, 2014 to 2021). Intense feelings of nervousness, tension, or panic often arise in response to interpersonal stresses. "Both Brinp1 knock-out lines exhibit increased activity, reduced sociability, reduced anxiety and impaired working memory." (PMID 27042284, 2016). "From the comprehensive behavioral test battery it was revealed that BRINP1-KO mice show several abnormal behaviors: increased locomotor activity, decreased anxiety-like behavior, poor social interaction, and mild deficit of working memory." (PMID 24528488, 2014). "BRINP1-KO mice showed abnormal behaviors: hyperactivity, decreased anxiety-like behaviors, poor social interaction, and slight impairment of working memory, all of which resemble symptoms of certain human psychiatric disorders." (PMID 24528488, 2014). "The fact that both Brinp1−/− and Brinp3−/− mice exhibit this phenotype, along with sociability changes, may indicate a role for both genes in regulating anxiety as well as sociability." (PMID 27826231, 2016). "Brinp1−/− mice generated by our group and others show hyperactivity, decreased body weight, reduced reproductive success, impaired short-term memory, altered anxiety response, and social communication impairments reminiscent of autism spectrum disorder (ASD)." (PMID 27826231, 2016). "In addition to these phenotypes, BRINP1-KO mice showed a set of abnormal behaviors: increase in locomotor activity, decreased anxiety-like behavior, poor social interaction, and slight deficit of working memory." (PMID 24528488, 2014). "For example, reduced anxiety is evident on the EPM for males only, whereas only female Brinp1−/− mice exhibited reduced grooming behaviour." (PMID 27042284, 2016).
autism spectrum disorder (3 papers, 2016 to 2021). A spectrum of developmental disorders that includes autism, and Asperger syndrome. "We, and others, have previously shown that Brinp1−/− mice exhibit behavior reminiscent of autism spectrum disorder (ASD) and attention deficit hyperactivity disorder (ADHD)." (PMID 27826231, 2016). "The increased cortical PV-positive interneuron density and altered behaviour of Brinp1−/− mice resemble features of a subset of human neurological disorders; namely autism spectrum disorder (ASD) and the hyperactivity aspect of attention deficit hyperactivity disorder (ADHD)." (PMID 27042284, 2016). "Absence of Brinp1 during development results in a behavioural phenotype resembling autism spectrum disorder (ASD), in which knock-out mice show reduced sociability and changes in vocalisation capacity." (PMID 27042284, 2016).
astrocytoma (2 papers, 2004 to 2019). "Reduced expression of BRINP1 caused by different mechanisms, such as promoter hypermethylation, has been revealed in a number of tumor types including lymphoproliferative malignancies, non-small cell lung carcinomas, and astrocytomas." (PMID 31083655, 2019).
schizophrenia (2 papers, 2014 to 2022). A major psychotic disorder characterized by abnormalities in the perception or expression of reality. "The disturbed hippocampal circuitry formed by BRINP1-deficiency could serve as an endophenotype for human psychiatric disorders such as schizophrenia and ADHD." (PMID 24528488, 2014). "Regardless of the alteration of neurogenesis, abnormal behaviors observed in BRINP1-KO mice are comparable to the symptoms of schizophrenia and ADHD." (PMID 24528488, 2014). "In addition, BRINP1-KO mice showed a characteristic set of abnormal behaviors which provides a useful animal model for a group of human psychiatric disorders such as schizophrenia and ADHD." (PMID 24528488, 2014). "This is a similar profile to other “schizophrenia-like” DISC1 and BRINP1 mouse models." (PMID 36407114, 2022).
Cognitive impairment (1 paper, 2016). Abnormal cognition is characterized by deficits in thinking, reasoning, or remembering. "The short-term memory impairment of Brinp1−/− mice may model cognitive impairment evident in a subset of autistic patients, or possibly psychiatric disorders that show association with the BRINP1 locus." (PMID 27042284, 2016).
glioma (1 paper, 2021). A benign or malignant brain and spinal cord tumor that arises from glial cells (astrocytes, oligodendrocytes, ependymal cells). "A series of genes such as EN1, S100A4, ANXA1, PDPN, IGFBP2 and CHI3L1 were upregulated in radiotherapy treated glioma patients, while other genes such as PRLHR, SFRP2, BRINP1, TRIM67, LHX5, KCNIP2 and NSG2 were downregulated." (PMID 34852024, 2021).
male pattern baldness (1 paper, 2020). "Out of 13 SNPs included in our predictive models for hair greying, 6 (FGF5 rs7680591, RUNX1 rs68088846, IRF4 rs12203592, BRINP1 rs2416699, TEX41 rs10928235, GRID1 rs2814331) were previously associated with male pattern baldness (MPB)." (PMID 32758128, 2020).
meningioma (1 paper, 2019). A generally slow growing tumor attached to the dura mater. "BMP/retinoic acid inducible neural specific 1 (BRINP1), and PROM1 were significantly downregulated in DCC low expression meningiomas in five studies." (PMID 31083655, 2019).
vitiligo (1 paper, 2024). Generalized well circumscribed patches of leukoderma that are generally distributed over symmetric body locations and is due to autoimmune destruction of melanocytes. "Regarding ECA25, six significant genomic regions were identified, although genes related to biological processes associated with vitiligo (TXN, LPAR1, SLC46A2, PRPF4, TRIM32, STOM, BRINP1, and DAB2IP) were only found in five of them." (PMID 39199954, 2024).
tumor (16 papers, 2001 to 2025). "In contrast, inflamed phenotypes showed upregulation of BRINP1, a gene associated with immune cell differentiation and PD-L1 regulation in tumor cells, suggesting its role in fostering robust anti-tumor immune responses." (PMID 39751650, 2025). "The most highly correlated gene was BRINP1 which has been shown to influence the rate of proliferation in tumour cell lines, in part by modulating the activities of the steroid and retinoic acid receptors ERA, AR and RARA." (PMID 26479384, 2015). "Finally, the BRINP1 (BMP/retinoic acid inducible neural specific 1) gene is associated with hair-greying processes in humans, while the DAB2IP (DAB2 interacting protein) gene has been reported to play a role in tumour suppression and metastasis." (PMID 39199954, 2024).
neurodevelopmental disorder (4 papers, 2016 to 2021). A behavioral and cognitive disorder with onset during the developmental period that involves impaired or aberrant development of intellectual, motor, or social functions. "Genetic variation at the human BRINP2/ASTN1 and BRINP1/ASTN2 loci has been implicated in neurodevelopmental disorders." (PMID 27826231, 2016). "The associated SNPs map at the highly conserved ASTN2/BRINP1 locus at chr9q33.1–33.2, which contains five genes (ASTN2, BRINP1, TRIM32, TLR4 and C5) that have been previously associated with neurodevelopmental disorders (reviewed in29)." (PMID 34267256, 2021).
psychiatric disorder (4 papers, 2014 to 2021). A disorder characterized by behavioral and/or psychological abnormalities, often accompanied by physical symptoms. "Abnormal behaviors comparable to those of human psychiatric disorders such as hyperactivity and poor social behavior were observed in BRINP1-KO mice." (PMID 24528488, 2014). "BRINP1-KO mice showed several abnormal behaviors comparable to symptoms of human psychiatric disorders." (PMID 24528488, 2014). "In addition to the promoted neurogenesis in hippocampus, BRINP1-KO mice showed a set of abnormal behaviors comparable to the symptoms of human psychiatric disorders." (PMID 24528488, 2014). "Therefore, confirmation of the causal relationship between alterations of hippocampal neurogenesis and differentiation and abnormal behaviors of BRINP1-KO mice could provide important clues for etiological mechanisms of human psychiatric disorders related to the impairment of hippocampal functions." (PMID 24528488, 2014).
BRINP1 also shares sentences with these, for which no sentence is quoted: cancer (4 papers); bladder tumor (3); breast carcinoma (3); lung carcinoma (2); prostate carcinoma (2); attention deficit-hyperactivity disorder (1); autism (1); cardiovascular diseases (1); cervical cancer (1); colon cancer (1); developmental delay (1); dysplasia (1); epithelial dysplasia (1); gastric cancer (1); head and neck carcinoma (1); learning disability (1); leukaemia (1); leukoplakia (1); myocardial infarction (1); neurodegenerative disease (1); neurological disorders (1); non-small cell lung carcinoma (1); Obesity (1); oral carcinomas (1); oral squamous cell carcinomas (1); ovarian carcinoma (1); Parkinson disease (1).